NBN (nibrin)
Description:
Component of the MRN complex, which plays a central role in double-strand break (DSB) repair, DNA recombination, maintenance of telomere integrity and meiosis. The MRN complex is involved in the repair of DNA double-strand breaks (DSBs) via homologous recombination (HR), an error-free mechanism which primarily occurs during S and G2 phases. The complex (1) mediates the end resection of damaged DNA, which generates proper single-stranded DNA, a key initial steps in HR, and is (2) required for the recruitment of other repair factors and efficient activation of ATM and ATR upon DNA damage. The MRN complex possesses single-strand endonuclease activity and double-strand-specific 3'-5' exonuclease activity, which are provided by MRE11, to initiate end resection, which is required for single-strand invasion and recombination. Within the MRN complex, NBN acts as a protein-protein adapter, which specifically recognizes and binds phosphorylated proteins, promoting their recruitment to DNA damage sites. Recruits MRE11 and RAD50 components of the MRN complex to DSBs in response to DNA damage. Promotes the recruitment of PI3/PI4-kinase family members ATM, ATR, and probably DNA-PKcs to the DNA damage sites, activating their functions. Mediates the recruitment of phosphorylated RBBP8/CtIP to DSBs, leading to cooperation between the MRN complex and RBBP8/CtIP to initiate end resection. RBBP8/CtIP specifically promotes the endonuclease activity of the MRN complex to clear DNA ends containing protein adducts. The MRN complex is also required for the processing of R-loops. NBN also functions in telomere length maintenance via its interaction with TERF2: interaction with TERF2 during G1 phase preventing recruitment of DCLRE1B/Apollo to telomeres. NBN also promotes DNA repair choice at dysfunctional telomeres: NBN phosphorylation by CDK2 promotes non-homologous end joining repair at telomeres, while unphosphorylated NBN promotes microhomology-mediated end-joining (MMEJ) repair. Enhances AKT1 phosphorylation possibly by association with the mTORC2 complex.
Synonyms: hNbs1; NBS; NBS1; P95; ATV; AT-V2; AT-V1
Tractability: Small molecule: a structure with a bound ligand is known. PROTAC: UniProt records ubiquitination sites on it; ubiquitination databases record sites on it; its protein half-life has been measured.
Gene: Protein-coding gene on chromosome 8 (89,924,515 to 90,003,228, reverse strand). Ensembl gene ENSG00000104320.
Subcellular location: Nucleus; Chromosome; Nucleus, PML body; Chromosome, telomere
Subcellular location (Human Protein Atlas): Nucleoplasm; Golgi apparatus; Mitotic chromosome
Pathways (Reactome):
DNA Repair: HDR through Homologous Recombination (HRR); HDR through MMEJ (alt-NHEJ); HDR through Single Strand Annealing (SSA); Homologous DNA Pairing and Strand Exchange; Nonhomologous End-Joining (NHEJ); Presynaptic phase of homologous DNA pairing and strand exchange; Processing of DNA double-strand break ends; Recruitment and ATM-mediated phosphorylation of repair and signaling proteins at DNA double strand breaks; Resolution of D-loop Structures through Holliday Junction Intermediates; Resolution of D-loop Structures through Synthesis-Dependent Strand Annealing (SDSA); Sensing of DNA Double Strand Breaks
Disease: Defective HDR through Homologous Recombination Repair (HRR) due to PALB2 loss of BRCA1 binding function; Defective HDR through Homologous Recombination Repair (HRR) due to PALB2 loss of BRCA2/RAD51/RAD51C binding function; Defective homologous recombination repair (HRR) due to BRCA1 loss of function; Impaired BRCA2 binding to PALB2; Impaired BRCA2 binding to RAD51
Cell Cycle: G2/M DNA damage checkpoint
Cellular responses to stimuli: DNA Damage/Telomere Stress Induced Senescence
Reproduction: Meiotic recombination
Gene Ontology:
Molecular function: chromatin-protein adaptor activity; DNA-binding transcription factor binding; histone binding; phosphorylation-dependent protein binding; protein binding; protein serine/threonine kinase activator activity; damaged DNA binding
Biological process: DNA damage checkpoint signaling; DNA double-strand break processing; DNA strand resection involved in replication fork processing; double-strand break repair; double-strand break repair via alternative nonhomologous end joining; double-strand break repair via homologous recombination; mitotic G2 DNA damage checkpoint signaling; negative regulation of telomere capping; positive regulation of double-strand break repair; positive regulation of telomere maintenance; protection from non-homologous end joining at telomere; protein localization to site of double-strand break; R-loop processing; t-circle formation; telomere maintenance; telomere maintenance in response to DNA damage; telomere maintenance via telomere trimming; telomeric 3' overhang formation; homologous recombination; mitotic G2/M transition checkpoint; positive regulation of double-strand break repair via homologous recombination; protein K63-linked ubiquitination; regulation of cell cycle; regulation of DNA-templated DNA replication initiation; and 5 more
Cellular component: BRCA1-C complex; chromosome; chromosome, telomeric region; Mre11 complex; nuclear inclusion body; nucleolus; nucleoplasm; nucleus; PML body; site of double-strand break; chromosomal region; cytosol; replication fork
Genetic constraint (gnomAD): Loss-of-function variants: 62 observed, 72.48 expected, observed/expected ratio (o/e) 0.86, 90% interval 0.7 to 1.06. The upper end of that interval is the gene's LOEUF score, 1.06, which puts it in group 4 of 6, group 1 being the genes least tolerant of losing a copy. Missense variants: 773 observed, 781.34 expected, observed/expected ratio (o/e) 0.99, 90% interval 0.93 to 1.05. Synonymous variants: 284 observed, 272.98 expected, observed/expected ratio (o/e) 1.04, 90% interval 0.94 to 1.15.
Gene-disease validity (ClinGen):
ClinGen rates the evidence that NBN causes each of these diseases.
Nijmegen breakage syndrome (autosomal recessive): Definitive. Nijmegen breakage syndrome is a rare genetic disease presenting at birth with microcephaly, dysmorphic facial features, becoming more noticeable with age, growth delay, and later-onset complications such as malignancies and infections.
hereditary breast carcinoma (autosomal dominant): Refuted. Breast carcinoma that has developed in relatives of patients with history of breast carcinoma.
Homologues: Orthologues: chimpanzee NBN (99% identical), macaque NBN (95% identical), rabbit NBN (78% identical), guinea pig NBN (76% identical), pig NBN (76% identical), dog NBN (74% identical), mouse Nbn (71% identical), rat Nbn (69% identical), tropical clawed frog nbn (42% identical), zebrafish nbn (37% identical), Drosophila melanogaster nbs (22% identical).
Diseases named in the same sentence as NBN in open-access papers:
NBN is named in the same sentence as 124 diseases in open-access papers, as found by Europe PMC text mining. Sharing a sentence is not in itself a finding about the gene and the disease. The quoted sentences say what the papers report.
breast carcinoma (94 papers, 1995 to 2025). "Based on preliminary research that has suggested an increased risk for carriers, the NBN gene has been added to breast cancer multigene panels, with the c.657del5 mutation being associated with up to 30% of female breast cancer cases." (PMID 39274207, 2024). "In the absence of BRCA1/2 germline mutations, alterations in other specific homologous recombination (HR) genes, such as PALB2, CHEK2, ATM, and NBN, can lead to an increased risk of breast cancer development." (PMID 39272660, 2024). "NBN serves as an established breast cancer susceptibility gene in the latest guidelines, because many studies reported that NBN c.657del5 (a founder variant in the Slavic population) was associated with increased risk of breast cancer." (PMID 34606182, 2021). "A founder mutation of BRCA1, BRCA2, CHEK2, PALB2 and NBN was found in 13.3% of men with breast cancer in Poland." (PMID 34461861, 2021). "Among three genes in the MRN complex, the inherited NBN gene change has the strongest evidence to act as an intermediate-risk breast cancer gene." (PMID 30975222, 2019). "An intronic palindrome that is associated with one of the breast cancer gene (brca) NBN, that is in 8q21 region, shows significant changes in tumors ie., changes in seven tumors but no change in any normal samples." (PMID 28117658, 2016). "An insertion mutation was validated in the DNA repair gene NBN, which is altered in high-risk breast cancer." (PMID 27270314, 2016). "NBN mutations have shown to be associated with chromosomal rearrangements and instability, with increased risk for cancers including breast cancer." (PMID 28117658, 2016). "Breast cancer cell lines were screened by immunoblotting for NBN protein levels, and the NBN coding region was sequenced for mutation analysis." (PMID 24928521, 2014). "Our results indicate that the p.R215W mutation in the HCC1395 breast cancer cell line impairs NBN function, making this cell line a potentially useful cellular model for studying defective NBN protein within a mutant BRCA1 background." (PMID 24928521, 2014). "Results reported here establish that MRE11A, RAD50, and NBN are intermediate-risk breast cancer susceptibility genes and help to justify their inclusion on panel-based cancer susceptibility gene tests." (PMID 24894818, 2014). "In the present work, we evaluated the contribution of rare variants in the genes MRE11A, RAD50, and NBN to breast cancer risk." (PMID 24894818, 2014). "NBN mutation carriers confer elevated risks for a numerous types of cancers, including breast cancer, which can be estimated to a 2- to 3-fold increase, while family relatives display a higher rate of various forms of cancers." (PMID 23586058, 2013). "In fact, nibrin is at the crossroad of several pathways implicating genes already associated with breast cancer susceptibility and/or chromosomal instability disorders." (PMID 19523210, 2009). "Further analyses will be needed to fully ascertain the exact impact of those variants on breast cancer susceptibility, in particular for variants located in NBN promoter region." (PMID 19523210, 2009). "Further analyses will therefore be needed to ascertain the impact of rare variants and promoter variants of NBN on breast cancer susceptibility in other populations." (PMID 19523210, 2009). "It is notable that while certain NBN variants have previously been reported to increase breast cancer risk, the most recent evidence from a large-scale case–control analysis refutes (OR 0.90, 95% CI 0.67–1.20) an association of truncating NBN variants with breast cancer risk." (PMID 33917078, 2021).
breast carcinoma (continued). "Indeed, it was shown that mutations in the NBN gene are associated to an increase of a risk of breast cancer through the double-stranded break repair mechanism." (PMID 30857266, 2019). "We showed that the germline p.Ile171Val mutation in NBN, one of the M/R/N genes, may be considered a risk factor in the development of solid malignant tumors, including breast cancer, larynx and colorectal cancer or acute lymphoblastic leukemia (ALL)." (PMID 29678143, 2018). "Regarding the NBN gene, several studies clearly shown the elevated risk of breast cancer with a positive NBN testing result, however, this risk assessment was limited to a specific NBN pathogenic variant, c.657_661del (p.Lys219Asnfs*16), observed frequently in the Slavic population." (PMID 30441849, 2018). "CHEK2 and NBN are also known breast cancer associated genes that were found to each have an interesting variant of unknown significance in our sample." (PMID 28591191, 2017). "Furthermore, we found double heterozygous breast cancer mutations in two patients with TNBC (one patient was BRCA1/NBN) and two patients with Hn-TNBC." (PMID 26083025, 2015). "We report for the first time the identification and characterization of a breast cancer cell line containing a NBN mutation that affects its function, providing a potentially useful cellular model for studying defective NBN protein within a mutant BRCA1 background." (PMID 24928521, 2014). "Likewise, heterozygous carriers of the NBN c.657del5 mutation present increased risk of malignant tumor development, especially breast cancer, prostate, and colorectal cancer." (PMID 24093751, 2013). "Heterozygous mutations carriers in genes of the MRN complex seem to be predisposed to cancer development, especially heterozygous NBN mutation carriers have an elevated risk of acute lymphoblastic leukemia, melanoma, colon and rectum cancer, prostate and breast cancer." (PMID 24079363, 2013). "Our analysis suggests that the variant c.-242-110delAGTA identified in our cohort of breast cancer individuals and located in the promoter region of the NBN gene may be associated with an increased risk of breast cancer." (PMID 19523210, 2009). "We focused on Polish founder mutations in BRCA1, BRCA2, PALB2, CHEK2, NBN and RECQL (18 alleles), which account for one-half of Polish breast cancer families." (PMID 40770660, 2025). "In HER2- and MDM2-enriched breast cancer subtypes, NBN plays a role in doxorubicin, paclitaxel, and carboplatin resistance via its involvement in DNA repair and homologous recombination." (PMID 41375077, 2025). "Variants involving ATM, CHEK2, BRIP1, RAD51C, RAD51D, NBN and BARD1 are known to be associated with a moderately increased risk of breast cancer and a lifetime risk of around 25%." (PMID 38439815, 2024). "This is expected, given that HRDetect was trained on genomes from patients with BRCA1/BRCA2 LOF in breast cancer, whereas NBN plays a role further upstream of BRCA1/BRCA2 in the repair of DNA double-strand breaks." (PMID 38561473, 2024). "In the present study, we evaluated the association of tag SNPs in HRR genes NBN, RAD51 and XRCC3 with toxicity and outcome of adjuvant RT and tumor differentiation grade in early HER2-positive breast cancer patients." (PMID 36139526, 2022). "Apart from rare mutations, several common single nucleotide polymorphisms (SNPs) in various HRR genes, including NBN, RAD51, and XRCC3, were reported to affect DNA repair capacity and were previously associated with altered breast cancer risk." (PMID 36139526, 2022).
breast carcinoma (continued). "Among the genes commonly included in breast cancer panels is NBN, which encodes the protein nibrin: one of the components of the MRN complex, which is essential for DNA double-strand break repair." (PMID 34072463, 2021). "In Jamaica, we found a 5.5% (10 of 183) rate of inherited breast cancer with germline variants in BRCA1, BRCA2, PALB2, STK11, and NBN genes." (PMID 33646313, 2021). "The NBN gene has been included in breast cancer (BC) multigene panels based on early studies suggesting an increased BC risk for carriers, though not confirmed by recent research." (PMID 34072463, 2021). "In the current study, we evaluated the frequency of 20 recurrent mutations in six genes (BRCA1, BRCA2, CHEK2, PALB2, NBN and RECQL) in 165 men diagnosed with breast cancer in Poland." (PMID 34461861, 2021). "We estimated the prevalence of 20 alleles in six genes (BRCA1, BRCA2, CHEK2, PALB2, NBN, RECQL) in 165 Polish male breast cancer patients." (PMID 34461861, 2021). "Both of these patients were diagnosed with bilateral breast cancer and both carried a mutation in the PALB2 gene.a- for BRCA1, CHEK2, PALB2, NBN mutation frequencies in cancer-free controls were from our previous studies." (PMID 34461861, 2021). "Twenty founder alleles in BRCA1, BRCA2, CHEK2, NBN, PALB2 and RECQL genes are responsible for the majority of hereditary breast cancers in Polish women." (PMID 34461861, 2021). "Nineteen genes from these gene sets were identified to be amplified and upregulated in breast cancer but only five of them NBN, PRKDC, RFWD2, UBE2T, and YWHAZ meet criteria in all breast cancer molecular subtypes." (PMID 33925616, 2021). "In our previous study, twenty recurrent mutations were found in six breast-cancer-predisposing genes (BRCA1, BRCA2, CHEK2, PALB2, NBN, and RECQL) in Polish breast cancer patients." (PMID 32824581, 2020). "There are twenty recurrent mutations in six breast-cancer-predisposing genes in Poland (BRCA1, BRCA2, CHEK2, PALB2, NBN, and RECQL)." (PMID 32824581, 2020). "Biallelic carriers of PVs in other, dominant breast cancer susceptibility genes such as BRCA2, ATM, PALB2, and NBN are known to have more severe cancer phenotypes than monoallelic carriers." (PMID 31993860, 2020). "The goal of the current study was to estimate the prevalence of twenty alleles in six genes, BRCA1/2, CHEK2, PALB2, NBN, and RECQL, in Polish early-onset breast cancer patients." (PMID 32824581, 2020). "In total, the panel covered about 80% of all BRCA1/2, CHEK2, PALB2, NBN, and RECQL mutation detection in Polish high-risk families with breast cancer." (PMID 32824581, 2020). "We genotyped 2464 women with breast cancer diagnosed below age 41 years for twenty recurrent germline mutations in six genes, including BRCA1, BRCA2 CHEK2, PALB2, NBN, and RECQL." (PMID 32824581, 2020). "Reported DSB repair variants in breast cancer comprise PALB2, NBN, RAD51, ATM, CHEK2, ATR, RAD50, and WRN." (PMID 31658756, 2019). "An additional 5.1% (95% CI: 2.4–8.5) are estimated to carry a pathogenic allele of a moderate-risk breast cancer susceptibility gene (i.e., ATM, BARD1, CHEK2, or NBN) bringing the total proportion of estimated carriers to 10.4% (95% CI: 6.5–14.9)." (PMID 29945567, 2018). "Female CHEK2 and NBN mutation carriers are at an increased lifetime risk of developing breast cancer (2-fold for CHEK2 and 3-fold for NBN carriers)." (PMID 28591191, 2017). "For example, for NBN (a breast cancer suppressor), one target gene of the key regulator hsa-miR-499-3p has also been reported to be associated with increased risk of breast cancer." (PMID 24848634, 2014).